OR11H12 (olfactory receptor family 11 subfamily H member 12)
Description:
Odorant receptor.
Tractability: Antibody: UniProt places it where antibodies can reach, with medium confidence; UniProt predicts a signal peptide or a membrane-spanning region; its Gene Ontology location is reachable by antibodies, with medium confidence.
Gene: Protein-coding gene on chromosome 14 (18,601,117 to 18,602,097, forward strand). Ensembl gene ENSG00000257115.
Subcellular location: Cell membrane
Gene Ontology:
Molecular function: G protein-coupled receptor activity; olfactory receptor activity
Biological process: detection of chemical stimulus involved in sensory perception of smell; G protein-coupled receptor signaling pathway
Cellular component: membrane; plasma membrane
Genetic constraint (gnomAD): Loss-of-function variants: 10 observed, 11.35 expected, observed/expected ratio (o/e) 0.88, 90% interval 0.54 to 1.49. The synonymous counts are far from expectation, so gnomAD's model fits this gene poorly and the ratio says little. Missense variants: 119 observed, 186.95 expected, observed/expected ratio (o/e) 0.64, 90% interval 0.55 to 0.74. Synonymous variants: 38 observed, 60.98 expected, observed/expected ratio (o/e) 0.62, 90% interval 0.48 to 0.82.
Homologues: Orthologues: dog OR11H12 (80% identical). Paralogues in human: OR11H1 (95% identical), OR11H2 (94% identical), OR11H6 (62% identical), OR11H4 (60% identical), OR11G2 (58% identical), OR11H7 (55% identical), OR11A1 (42% identical), OR9G1 (40% identical), OR10X1 (36% identical), OR9A2 (33% identical), OR9A4 (33% identical), OR9A1P (33% identical), and 21 more.
Diseases named in the same sentence as OR11H12 in open-access papers:
OR11H12 is named in the same sentence as 4 diseases in open-access papers, as found by Europe PMC text mining. Sharing a sentence is not in itself a finding about the gene and the disease. The quoted sentences say what the papers report.
autism (1 paper, 2022). Persistent deficits in social interaction and communication and interaction as well as a markedly restricted repertoire of activity and interest as well as repetitive patterns of behavior. "The detection of variants within the OR11H12 gene encoding an olfactory receptor is also not surprising, as rare and common variants in at least several OR genes have been reported in association with autism, such as OR2M4, OR2T10, and OR52M1." (PMID 35627305, 2022).
hyperlipidemia (1 paper, 2022). "Moreover, neuropathy, ketoacidosis and hyperlipidemia were associated with significant upregulations in expression of PPP1R1B, TCEB3C and OR11H12 as shown in Boxplots 8E, 8G and 8J, respectively." (PMID 36175575, 2022).
tumor (1 paper, 2021). "The OR11H12 gene exhibited two somatic missense mutations in the primary tumor tissue of case 1 (p.Y233H and p.L235I) and was found mutated in a single PTC case from the TCGA dataset." (PMID 33827048, 2021).
OR11H12 also shares sentences with these, for which no sentence is quoted: neuropathy (1 paper).